SOX9 (SRY-box transcription factor 9)
Diseases named in the same sentence as SOX9 in open-access papers (continued):
Sharing a sentence is not in itself a finding about the gene and the disease.
disc degeneration (10 papers, 2011 to 2025). "This supports our use of Agc1‐CreERT2 to conditionally delete Sox9 in the intervertebral disc to explore the signaling pathways involved in disc degeneration and associated pain mechanisms." (PMID 40012719, 2025). "Deletion of Sox9 in Aggrecan‐expressing IVD tissues affects disc degeneration and associated pain behaviors through the β–catenin–CCL2 pathway." (PMID 40012719, 2025). "These should include overexpression studies and functional assays to validate the therapeutic potential of targeting Sox9 in mitigating disc degeneration‐associated pain." (PMID 40012719, 2025). "Elevated β‐catenin and CCL2 levels in Sox9‐deleted tissues suggest that the β‐catenin‐CCL2 pathway plays a crucial role in the inflammatory response and pain associated with disc degeneration." (PMID 40012719, 2025). "We identified four genes (SOX9, FLVCR1, NR5A1 and UCHL1) associated with mitochondrial dysfunction that play an important role in the progress of disc degeneration." (PMID 36267810, 2022). "A recent study from Maria demonstrated that SOX9 mutant mice experience early-onset, progressive disc degeneration characterized by increased cell death, alterations in ECM organization, and distinct transcriptomic changes in the NP and AF compartments." (PMID 36267810, 2022). "The reduction of type II collagen, aggrecan, and SOX-9 in NPCs is usually related to a severe disc degeneration." (PMID 33505586, 2021). "In this study, we first demonstrated that RCAN1.4 is positively associated with disc degeneration and that hypoxia-induced downregulation of RCAN1.4 activated the calcineurin/NFAT signaling pathway to facilitate SOX9 and MMP13 expression." (PMID 32467610, 2020). "This study investigated the efficacy of Sox9-transduced BMSCs for IVD repair in a well-established rabbit disc degeneration model." (PMID 24691466, 2014). "SIRT1 treatment significantly reduced aggrecan, Sox9 and collagen type 2 mRNA expression in a dose-dependent manner in all disease classes and disc degeneration grades." (PMID 22152608, 2011). "SOX-9 and collagen II are protective genes against chondrogenesis and disc degeneration." (PMID 34416893, 2021). "In a second phase, between day 7 and day 14, IVD cells combined with DWJM showed a down-regulation of SOX2 and SOX9 together with an up-regulation of TRPS1, a chondrogenic transcription factor previously identified by us as chondroprotective and associated with the lower grade of disc degeneration." (PMID 32292779, 2020). "Our findings reveal that the disruption of Sox9 enhances β‐catenin activity and CCL2 expression, contributing to disc degeneration." (PMID 40012719, 2025). "The aim of our study was to investigate the role of Sox9 in maintaining intervertebral disc (IVD) health and to explore how its deletion impacts disc degeneration and pain behaviors." (PMID 40012719, 2025). "For example, Sox9-transfected MSCs were used to treat NP degeneration in rabbits, and BMSC-derived exosomes were shown to attenuate IDD in a caudal disc degeneration model in rats." (PMID 31666429, 2019). "Our results showed that CCL2 is also increased in Sox9‐deleted tissues, suggesting that the dysregulation of the β–catenin–CCL2 pathway due to Sox9 deletion may drive the inflammatory response and pain observed in degenerative disc disease." (PMID 40012719, 2025).
Stroke (10 papers, 2011 to 2024). Sudden impairment of blood flow to a part of the brain due to occlusion or rupture of an artery to the brain. "Lineage tracing showed that after both SCI and stroke, over 90% of Gfap plus Sox9-positive lesion border astrocytes also expressed Aldh1l1-CreERT-tdT, indicating that these cells derived from local mature astrocytes." (PMID 38907165, 2024). "The circRNAs originating from the DGKB gene (circ_Dgkb_13, circ_Dgkb_14, and circ_Dgkb_10) collectively target SOX9 via miR-124-3p, thus affecting axonal budding after stroke." (PMID 34868302, 2021). "SOX9 expression levels in astrocytes also are elevated after CNS insults as assessed with stroke and amyotrophic lateral sclerosis (ALS) models." (PMID 29590625, 2018). "Together, we assume that Txnip+/Rbp1+/Sox9+ astrocytes could engulf C1q+ synapses at the recovery stage of stroke." (PMID 34836962, 2021). "LRRK2, CALM1, CXCR4, TLR4, CTNNB1, and CXCR2 may be implicated in AF and the hub-genes of CD19, FGF9, SOX9, GNGT1, and NOG may be associated with stroke." (PMID 30760287, 2019). "However, silencing of SOX9 contributes to neuroprotection and recovery after stroke." (PMID 33791290, 2020). "Previous studies have identified several targets of miR-124, such as PTB/hnRNP I (PTBP1) and SRY-box transcription factor (Sox9), which participate in neuronal differentiation; and Jagged1 (JAG1), which mediates neurogenesis in stroke." (PMID 33841091, 2021). "In both SCI and stroke, about 75% of the Pdgfra-CreERT-tdT-positive cells in the lesion border zone were Olig2-positive but Gfap-negative and Sox9-negative OPCs." (PMID 38907165, 2024). "However, stroke did not significantly increase Sox9 levels in SVZ neural progenitor cells (1.2±0.2 in ischemic vs 1.0±0.1 in non-ischemic, n = 3, p = 0.23)." (PMID 21887253, 2011). "However, the present study showed that stroke did not significantly change Sox9 expression." (PMID 21887253, 2011).
cartilage disease (9 papers, 2018 to 2024). Softening and degeneration of the CARTILAGE. "SOX9 is the master regulator of chondrocyte and cartilage homeostasis, and its impaired function is implicated in cartilage disease." (PMID 39344191, 2024). "The key role of Sox9 in the treatment of cartilage diseases has been frequently reported; however, the mechanisms by which RNA modifications regulate Sox9 are less understood." (PMID 35614315, 2022). "A prior study pointed out that SOX9 mediates adaptation to hypoxia in OA patients exhibiting aggressive cartilage disease." (PMID 34760015, 2021). "Sox9 plays a critical role in chondrogenesis, bone formation, and the treatment for cartilage diseases." (PMID 32294879, 2020). "Past research has reported that PACAP play an important role in cartilage diseases by regulating SOX family member molecules such as SOX5, SOX6, SOX9." (PMID 39619607, 2024).
fibrosis (9 papers, 2017 to 2025). the formation of excess fibrous connective tissue in an organ or tissue in a reparative or reactive process. "In vivo loss of SOX9 attenuated cardiac fibrosis in response to ischemic injury, whereas sustained SOX9 expression was associated with experimental fibrosis." (PMID 36613933, 2022). "Our observed upregulation of SOX9 in SSc lung thus highlights its significance to PF and extends the emerging literature implicating SOX9 in multiple types of fibrosis, including tracheal, liver, cardiac, kidney, and lung." (PMID 37510994, 2023). "The downregulation of NEAT1 and overexpression of miR-139-5p suppress the expression of profibrotic markers in murine fibrosis models via targeting β-catenin/SOX9/TGF-β1 pathway." (PMID 34531378, 2021). "Recent research has shown a connection between cardiac fibrosis and SOX9." (PMID 39974732, 2025). "Moreover, the extent of SOX9 in biopsies from patients with chronic liver disease correlated with fibrosis severity and accurately predicted disease progression towards cirrhosis." (PMID 30559459, 2018). "In this study, we have studied SOX9 in patients with chronic liver disease where sequential liver biopsies enabled fibrosis severity and disease progression to be deciphered over time and examined the consequences of inactivating SOX9 in rodent models of parenchymal and biliary liver fibrosis." (PMID 29109128, 2017).
basal cell carcinoma (8 papers, 2013 to 2023). A carcinoma involving the basal cells. "In contrast, expression of SOX9 was readily detectable in the epithelial lineage of normal skin as well as in basal cell carcinoma, an epithelial skin cancer." (PMID 25629959, 2015). "Immunohistochemical staining showed that Sox9 is predominantly expressed in the basal layer of normal human skin epidermis, and highly expressed in several skin diseases including psoriasis, basal cell carcinoma, keratoacanthoma and squamous cell carcinoma." (PMID 23349860, 2013). "In addition, highly expressed SOX9 promotes proliferation of basal cell carcinoma by directly transcriptionally regulating mTOR, which is a crossover pathway between hedgehog signaling and PI3K/AKT/mTOR pathways." (PMID 35563098, 2022). "Sox9 is also reported to be upregulated in brain tumors and basal cell carcinomas." (PMID 29970901, 2018). "It has been demonstrated that Sox9 is expressed in all subtypes of basal cell carcinoma (BCC)." (PMID 23349860, 2013). "Basal cell carcinoma has also been shown to express the epithelial stem cell markers CK19, LGR5, LRIG1, and SOX9." (PMID 34331569, 2021).
bladder cancer (8 papers, 2008 to 2025). "On the other hand, epigenetic changes of SOX9 were associated with the aggressiveness of bladder cancer." (PMID 31057614, 2019). "The association of SOX9 hypermethylation with tumour progression and clinical outcome suggests its relevant clinical implications at stratifying patients affected with bladder cancer." (PMID 18087279, 2008). "SOX9 was tested to be a candidate gene for hypermethylation-associated inactivation in bladder cancer cells." (PMID 18087279, 2008). "It provides a mechanistic explanation for the observed loss of SOX9 in uroepithelial malignancies, demonstrating transcriptional silencing by promoter CpG island hypermethylation in bladder cancer cell lines." (PMID 18087279, 2008). "Moreover, SOX9 methylation was associated with tumour grade and overall survival of bladder cancer patients." (PMID 18087279, 2008). "The expression of Wnt target Sox9 was upregulated in early bladder carcinogenesis (BBN group compared to NT group), which is in accordance with studies showing upregulation of Sox9 in bladder cancer." (PMID 32605249, 2020). "Having observed promoter hypermethylation in bladder cancer cell lines by bisulphite sequencing, specific MS-PCR was performed for SOX9." (PMID 18087279, 2008). "Mechanistically, it is important to evaluate the cellular consequences of the methylation of the promoter of SOX9 in bladder cancer cells." (PMID 18087279, 2008). "Bladder cancer cell lines hypermethylated for SOX9 showed low transcript and protein expression as revealed by RT–PCR and western blot analyses." (PMID 18087279, 2008). "SOX9 was selected for further validation by bisulphite genomic sequencing and methylation-specific polymerase chain reaction in bladder cancer cells (n=11) and primary bladder tumours (n=101)." (PMID 18087279, 2008). "Overall, in vitro analyses demonstrated that the expression of SOX9 is aberrantly silenced by CpG island promoter hypermethylation in bladder cancer, observations especially supported by AZA reactivation analyses." (PMID 18087279, 2008). "Treatment of methylated and unmethylated bladder cancer cell lines with a DNA-demethylating agent served to further link SOX9 hypermethylation and gene silencing." (PMID 18087279, 2008). "In bladder cancer cell lines, the low expression of SOX9 was restored by a demethylating agent in methylated cancer cells." (PMID 18087279, 2008). "Methylation rates were closer to 60% in the larger series of bladder tumours, which confirmed that SOX9 hypermethylation is a frequent event in bladder cancer." (PMID 18087279, 2008). "Methylation status and expression results of SOX9 correlated to high extent among a variety of bladder cell lines representing the spectrum of bladder cancer progression in vitro." (PMID 18087279, 2008). "Using a high-throughput epigenomic approach with CpG arrays, we identify novel candidates such as SOX9, presenting CpG island promoter hypermethylation in bladder cancer." (PMID 18087279, 2008). "Furthermore, CPX treatment reduced the expression of bladder cancer stem cell marker proteins SOX9 and CD44." (PMID 34059639, 2021). "MYC, EZH2 and SOX9 are known to be repressed in response to BET inhibition in several malignancies, such as medulloblastoma, bladder cancer and myelofibrosis, but as yet the effect of JQ1 on these genes in TNBC has not been explored." (PMID 32166583, 2020). "Exposure of methylated bladder cancer cell lines to the demethylating drug, AZA, restored expression of SOX9 at the transcript level in the J82 cell line." (PMID 18087279, 2008).
intervertebral disc degeneration (8 papers, 2014 to 2025). "Subsequently, the molecular mechanisms underlying pain associated with intervertebral disc degeneration due to Sox9 deletion were examined." (PMID 40012719, 2025). "The accelerated chondrogenesis of hMSCs can be achieved by co-transfection of Sox9 and TGFβ1 resulting in the cure of the manifestations associated with intervertebral disc degeneration." (PMID 37007782, 2023). "In this study, we therefore employed the Sox9 conditional knockout mouse to elucidate the relationship between intervertebral disc degeneration and pain behavior, as well as to identify the specific signaling pathways implicated in this process." (PMID 40012719, 2025). "This study investigates the mechanism of intervertebral disc degeneration via the β‐catenin/CCL2 pathway in Sox9 conditional knockout mice." (PMID 40012719, 2025). "The AF tissue displayed a marked loss of normal lamellar organization, and the interface region showed undefined boundaries between the NP–AF and EP–AF, suggesting that Sox9 conditional deletion leads to intervertebral disc degeneration." (PMID 40012719, 2025). "This study demonstrates that Sox9 deletion leads to severe intervertebral disc degeneration, characterized by disrupted matrix organization and increased inflammation, without mechanical herniation." (PMID 40012719, 2025). "Circ_15698 accelerated ECM accumulation in diabetic nephropathy.Circ_4099 regulated ECM synthesis by arresting miR-616-5p to inhibit SOX9 in intervertebral disc degeneration." (PMID 35068324, 2022). "In addition, the postnatal conditional inactivation of Sox9 leads to intervertebral disc degeneration." (PMID 40012719, 2025). "We demonstrate that the Sox9 regulation of β‐catenin, CCL2, and GDNF constitutes a pivotal mechanism in pain signaling, suggesting that modulation of this pathway may represent a promising therapeutic strategy for intervertebral disc degeneration and its concomitant pain." (PMID 40012719, 2025).
invasive carcinoma (8 papers, 2012 to 2024). A carcinoma that is not confined to the epithelium, and has spread to the surrounding stroma. "In Pten-deficient mouse prostate, we and other groups have demonstrated that prostate-specific Sox9 overexpression promotes the development of invasive carcinoma." (PMID 38687617, 2024). "A correlation between increased SOX9 expression and vascular invasion was observed in invasive carcinomas." (PMID 38002064, 2023). "This is consistent with the fact that SOX9 is highly expressed in invasive carcinomas in urothelial carcinoma tissue." (PMID 38002064, 2023). "In urothelial carcinomas, SOX9 is significantly upregulated in invasive carcinomas and plays an important role in determining their invasive potential." (PMID 38002064, 2023). "Low expression of SOX9 in non-invasive carcinoma was also consistent with the in vitro results in urothelial carcinoma tissues." (PMID 38002064, 2023). "Surprisingly, we find that, although later in invasive carcinoma SOX9 is generally expressed at low levels, its expression is higher in a subset of SQCCs with less squamous identity and worse clinical outcome." (PMID 27880766, 2016). "Together, this suggests that Sox9 deletion after mPIN initiation cannot prevent progression from mPIN to invasive carcinoma." (PMID 22761195, 2012). "The increased expression of SOX9 in invasive carcinoma was also investigated at the mRNA level." (PMID 38002064, 2023). "Moreover, deletion of Sox9 inhibits the progression of ductal-like lesions to invasive carcinoma, implying the crucial role of Sox9 as a driver of BLBC lineage reprogramming and tumor progression." (PMID 34298815, 2021). "Furthermore, SOX9 deletion inhibits the progression of ductal carcinoma in situ (DCIS)-like lesions to invasive carcinoma." (PMID 32521267, 2020). "In the presence of oncogenic KRAS, TRIM29 subsequently upregulates SRY-Box transcription factor 9 (SOX9), which accelerates the formation of pancreatic intraepithelial neoplasia and progression to invasive carcinoma." (PMID 34988104, 2021).
pancreatitis (8 papers, 2016 to 2024). Inflammation of the pancreas. "IF staining showed that SOX9+ cells were reduced in the pancreases of Reg4−/− mice compared to Wt mice during pancreatitis." (PMID 38769308, 2024). "No detectable SOX9 or ST6GAL1 was observed in healthy WT acinar cells (saline control), whereas numerous cells within WT pancreatitis tissues (cerulein) coexpressed amylase, SOX9, and ST6GAL1." (PMID 37643018, 2023). "In the model of cerulein induced pancreatitis, mice with conditional knockout of ETV5 exhibit delayed recovery from the inflammation and associate with decreased SOX9 expression in pancreas." (PMID 36872348, 2023). "After induction of acute (W1) or chronic (W3) pancreatitis, SOX9 and CK19 expression was detected in metaplastic acini of WT and ElaCER Erbb2KO mice." (PMID 32251323, 2020). "Consistent with previous studies, both AGR2+/+ wild-type and AGR2-/-null mice with pancreatitis showed a marked increase in nuclear SOX9 in acinar cells." (PMID 27764193, 2016). "In pancreatic ductal cells, the luciferase reporter assay demonstrates that upregulated ETV5 increases the activity of SOX9 promoter, indicating ETV5 might be an upstream regulator of SOX9 during pancreatitis." (PMID 36872348, 2023). "While, SOX9−/− mice undergo the cerulein induced pancreatitis maintain ETV5 expression." (PMID 36872348, 2023). "Interestingly, H&E staining and Sox9 (a prominent marker of pancreatitis) immunostaining of pancreatic tissues indicated that pancreatitis affected the acinar compartment, but did not cause formation of remnant islets." (PMID 32371554, 2020). "Our recent studies further showed that SOX9 could be induced by NFATC1 and NFATC4 in response to EGFR activation and pancreatitis, which promote ADM and PanIN." (PMID 30425728, 2018). "Importantly, the ectopic expression of ST6GAL1 in acinar cells induces a pronounced upregulation in a ductal gene network (in the absence of either pancreatitis or the KRAS oncogene), as evidenced by RNA-Seq results and staining of SC tissues for SOX9, KRT8, and KRT19." (PMID 37643018, 2023).
Pierre-Robin sequence (8 papers, 2012 to 2025). Pierre Robin malformation is a sequence of developmental malformations characterized by micrognathia (mandibular hypoplasia), glossoptosis and cleft palate. "Deletions encompassing an enhancer cluster 1.45 megabases upstream of SOX9 (EC1.45) cause Pierre Robin sequence, a craniofacial disorder characterised by underdevelopment of the lower jaw and associated with cleft palate." (PMID 41208708, 2025). "Mutations in SOX9 enhancers upstream of SOX9 can also be associated with isolated craniofacial anomalies of the CMPD syndrome called Pierre Robin sequence (PRS; OMIM: 261800)." (PMID 33810596, 2021). "SOX9 mutations have been identified in patients with Pierre Robin sequence and campomelic (or acampomelic) dysplasia with or without sex reversal." (PMID 33577554, 2021). "Interestingly, the activity of this element appears to be dependent on binding of the SOX9 TF, which has been associated with a craniofacial disorder with overlapping clinical features called Pierre Robin sequence (PRS), suggesting that SATB2 regulation might be primarily driven by SOX9." (PMID 32973355, 2021).